TAS2R5 (taste 2 receptor member 5)
Description:
Receptor that may play a role in the perception of bitterness and is gustducin-linked. May play a role in sensing the chemical composition of the gastrointestinal content. The activity of this receptor may stimulate alpha gustducin, mediate PLC-beta-2 activation and lead to the gating of TRPM5.
Synonyms: T2R5
Tractability: Antibody: its Gene Ontology location is reachable by antibodies, with high confidence; UniProt predicts a signal peptide or a membrane-spanning region. PROTAC: a small molecule that binds it is known.
Target class: Membrane receptor; Taste receptor (taste family GPCR); Taste family G protein-coupled receptor
Gene: Protein-coding gene on chromosome 7 (141,790,217 to 141,791,367, forward strand). Ensembl gene ENSG00000127366.
Subcellular location: Membrane
Subcellular location (Human Protein Atlas): Nucleoli; Nucleoplasm; Cytoplasmic bodies
Pathways (Reactome):
Signal Transduction: Class C/3 (Metabotropic glutamate/pheromone receptors); G alpha (i) signalling events
Sensory Perception: Sensory perception of sweet, bitter, and umami (glutamate) taste
Gene Ontology:
Molecular function: bitter taste receptor activity; protein binding; taste receptor activity; G protein-coupled receptor activity
Biological process: detection of chemical stimulus involved in sensory perception of bitter taste; chemosensory behavior; G protein-coupled receptor signaling pathway; sensory perception of taste
Cellular component: membrane; plasma membrane
Genetic constraint (gnomAD): Loss-of-function variants: 17 observed, 22.68 expected, observed/expected ratio (o/e) 0.75, 90% interval 0.51 to 1.12. The upper end of that interval is the gene's LOEUF score, 1.12, which puts it in group 4 of 6, group 1 being the genes least tolerant of losing a copy. Missense variants: 339 observed, 373.79 expected, observed/expected ratio (o/e) 0.91, 90% interval 0.83 to 0.99. Synonymous variants: 120 observed, 145.68 expected, observed/expected ratio (o/e) 0.82, 90% interval 0.71 to 0.96.
Homologues: Orthologues: chimpanzee TAS2R5 (97% identical), macaque TAS2R5 (93% identical), dog TAS2R5 (75% identical), tropical clawed frog t2r15 (23% identical), tropical clawed frog tas2r13 (22% identical), tropical clawed frog tas2r4 (22% identical), tropical clawed frog t2r10 (21% identical), tropical clawed frog t2r2 (21% identical), tropical clawed frog tas2r7 (20% identical), tropical clawed frog t2r5 (20% identical), tropical clawed frog t2r6 (20% identical), tropical clawed frog t2r8 (20% identical), and 5 more. Paralogues in human: TAS2R7 (27% identical), TAS2R20 (26% identical), TAS2R38 (26% identical), TAS2R46 (26% identical), TAS2R9 (26% identical), TAS2R50 (25% identical), TAS2R1 (25% identical), TAS2R39 (25% identical), TAS2R43 (25% identical), TAS2R13 (25% identical), TAS2R4 (25% identical), TAS2R10 (24% identical), and 11 more.
Diseases named in the same sentence as TAS2R5 in open-access papers:
TAS2R5 is named in the same sentence as 16 diseases in open-access papers, as found by Europe PMC text mining. Sharing a sentence is not in itself a finding about the gene and the disease. The quoted sentences say what the papers report.
asthma (1 paper, 2019). "TAS2R5 has been found to be overexpressed in asthma children and might have anti-inflammatory function by regulating cytokines, indicating its multifunctional characteristic." (PMID 31118907, 2019).
cervical squamous cell carcinoma (1 paper, 2022). A squamous cell carcinoma arising from the cervical epithelium. "Notably, statistically significant survival associations were identified for TAS2R5 in cervical squamous cell carcinoma (p < 0.001), TAS2R20 in esophageal adenocarcinoma (p = 0.044), and TAS2R4, TAS2R20, and TAS1R3 in prostate adenocarcinoma (p = 0.03, p = 0.033, and p = 0.023, respectively)." (PMID 35624283, 2022).
colon cancer (1 paper, 2024). "Utilizing univariate Cox regression analysis, we identified seven TAS2Rs genes associated with prognosis in colon cancer patients, including TAS2R4, TAS2R5, TAS2R14, TAS2R19, TAS2R20, TAS2R31, and TAS2R38." (PMID 38999959, 2024). "Our results show that compared to normal colon tissue, the expression levels of multiple bitter taste receptor genes are elevated in colon cancer tissue, including TAS2R4, TAS2R5, TAS2R14, TAS2R19, TAS2R20, TAS2R31, and TAS2R38." (PMID 38999959, 2024). "Differential expression analysis results revealed that compared to normal colon tissue, colon cancer samples exhibited elevated expression levels of TAS2R1, TAS2R4, TAS2R5, TAS2R14, TAS2R19, TAS2R20, and TAS2R38 (p < 0.05), with the exception of TAS2R60, which was downregulated." (PMID 38999959, 2024).
COVID-19 (1 paper, 2025). A disease caused by infection with severe acute respiratory syndrome coronavirus 2. "Additionally, two alleles in TAS2R1 and TAS2R5 were associated with the presence of nucleocapsid antibody, and two alleles in TAS2R1 and TAS2R62P were linked to lower odds of spike antibody seroconversion following COVID-19 vaccination or infection." (PMID 41153757, 2025).
schizophrenia (1 paper, 2019). A major psychotic disorder characterized by abnormalities in the perception or expression of reality. "TAS2R5 was also found to be downregulated in the dorsolateral prefrontal cortex of schizophrenia postmortem brain tissues compared to healthy control brain tissues." (PMID 31118907, 2019).
tumor (1 paper, 2022). "Changes in expression for TAS1R1, TAS1R3, TAS2R4, TAS2R5, TAS2R14, TAS2R19, and TAS2R20 had survival associations in at least one tumor histology." (PMID 35624283, 2022).
TAS2R5 also shares sentences with these, for which no sentence is quoted: acute myeloid leukaemia (1 paper); bipolar disorder (1); diabetes (1); esophageal adenocarcinoma (1); infection (1); inflammation (1); kidney clear cell carcinoma (1); prostate adenocarcinoma (1); respiratory diseases (1); stomatitis (1).